QKI (QKI, KH domain containing RNA binding)
Diseases named in the same sentence as QKI in open-access papers (continued):
Sharing a sentence is not in itself a finding about the gene and the disease.
colorectal cancer (11 papers, 2015 to 2025). A primary or metastatic malignant neoplasm that affects the colon or rectum. "Next, we investigated the role of QKI/PABPN1 axis in colorectal cancer cell proliferation and migration." (PMID 40052530, 2025). "Decreased expression levels and reduced nuclear localization of QKI in colorectal cancer cells attenuate PABPN1 LLPS, thereby promoting proximal APA sites, cell proliferation, and migration." (PMID 40052530, 2025). "Knockdown, overexpression and the KH domain mutant of QKI showed that QKI represses cell proliferation and migration in colorectal cancer cells, and these effects are also PABPN1-dependent to a certain extent." (PMID 40052530, 2025). "Western blot further confirms a substantial decrease in QKI protein levels in colorectal cancer cell lines (SW480 and SW620) compared with the normal cell line (NCM460)." (PMID 40052530, 2025). "In this study, we found that the reduced QKI expression and nuclear localization in colorectal cancer cells disrupt PABPN1 LLPS, promoting the usage of proximal poly(A) sites, cell proliferation and migration." (PMID 40052530, 2025). "TCGA data also show that QKI expression is significantly downregulated in several types of cancer tissues including colorectal cancer." (PMID 40052530, 2025). "QKI, a known tumor suppressor, is downregulated in colorectal cancer, and its promoter methylation is a potential biomarker for early disease detection." (PMID 40052530, 2025). "Knockdown of QKI in colorectal cancer cell lines SW480 and SW620 can significantly increase cell proliferation (P < 0.001) and migration rates (P < 0.01 or P < 0.001), as measured by the CCK-8 and Transwell assays, respectively." (PMID 40052530, 2025). "QKI has been reported to be targeted by miR-221, which targets QKI to potentiate tumorigenicity of human colorectal cancer stem cells." (PMID 33420414, 2021). "QKI was also downregulated in colorectal cancer tissues and cell lines, and was reported to inhibit cell cycle progression and invasion in colorectal cancer by negatively regulating microRNA-155." (PMID 32931453, 2020). "In addition to the reduced expression of QKI in colorectal cancer cells, we observed differences in its subcellular distribution between colorectal cancer cells (SW480 and SW620) and normal cells (NCM460)." (PMID 40052530, 2025). "Furthermore, the reduction of QKI expression and nuclear localization in colorectal cancer cells leads to decreased PABPN1 LLPS and shortened 3′ UTRs of other genes, which further promotes cell proliferation and migration." (PMID 40052530, 2025). "Among the candidate genes, QKI has been reported to be a colorectal cancer tumor suppressor." (PMID 40052530, 2025). "Given the reduced LLPS droplets of PABPN1 in colorectal cancer cells, we further investigated whether enhanced nuclear localization of QKI promotes PABPN1 LLPS." (PMID 40052530, 2025). "In addition to the observed reduction in QKI expression, we also found a decrease in the nuclear localization of QKI in colorectal cancer cells." (PMID 40052530, 2025). "Although studies have found that QKI is hypermethylated in colorectal cancer tissues compared with normal tissues, whether hypermethylation of QKI is a promising molecular marker for early detection of CRC has not been investigated." (PMID 36017498, 2022). "Although studies have suggested that QKI is a tumor suppressor gene, no studies have evaluated the diagnostic utility of QKI methylation in colorectal cancer (CRC)." (PMID 36017498, 2022). "Methylation of the QKI promoter, which reduces QKI expression, may be critical in colorectal cancer." (PMID 30774645, 2019). "Furthermore, the reduced expression level and nuclear localization of QKI in colorectal cancer cells negatively impacts PABPN1 LLPS, subsequently leading to increased usage of proximal APA sites and enhancing the proliferation and migration rates of cancer cells." (PMID 40052530, 2025).
colorectal cancer (continued). "Furthermore, QKI exhibits decreased expression levels and diminished nuclear localization in colorectal cancer cells, resulting in reduced PABPN1 phase separation, which, in turn, promotes alternative polyadenylation (APA), cell proliferation, and migration in colorectal cancer." (PMID 40052530, 2025). "In colorectal cancer (CRC), QKI is significantly downregulated, to the point of being absent, in part due to hypermethylation of its promoter." (PMID 39479357, 2024).
glioblastoma (11 papers, 2010 to 2024). The most malignant astrocytic tumor (WHO grade IV). "In the present study, statistical analysis of clinical specimens revealed, for the first time, that QKI is associated with shorter overall survival of patients with glioblastoma, supporting the notion that QKI functions as a tumor suppressor." (PMID 25971746, 2015). "QKI reduction is associated with the initiation and progression of glioblastoma, but its clinical significance in glioblastoma remains unexplored." (PMID 25971746, 2015). "Consistent with the repressive role of QKI in hnRNP F/H expression, the human qkI locus is frequently mutated in glioblastoma multiforme (GBM) derived from astrocytic origin identified by SNP-Chip analysis." (PMID 24792162, 2014). "In about 30% (6/20) of human glioblastomas, QKI expression has been altered, whereas in neurofibromas and meningiomas, QKI expression remained unchanged." (PMID 39479357, 2024). "In contrast, QKI has also been reported to promote tumor formation in both esophageal carcinoma and glioblastoma." (PMID 30059005, 2018). "Recent studies have revealed that QKI acts as a tumor suppressor gene, which is crucial for the tumorigenesis and progression of various malignant tumors, including glioblastoma, astrocytic glioma, oral squamous cell carcinoma, gastric cancer and colon cancer." (PMID 29861871, 2018). "Expression of QKI is reduced by deletion or translocation in a number of human cancers, such as glioblastoma, and prostate, oral, gastric and colorectal cancers, and functions as a tumor suppressor." (PMID 29064439, 2017). "Analyses using publicly available algorithms and the present results identified QKI as a direct target of miR-148a in glioblastoma." (PMID 25971746, 2015). "Here, we report microRNA-148a (miR-148a) overexpression in glioblastoma and that miR-148a directly suppressed Quaking (QKI), a negative regulator of TGF-β signaling." (PMID 25971746, 2015). "QKI suppresses TGF-β signaling in glioblastoma, and SKP1 is an essential component of the E3 ubiquitin ligase complex ROC1-SCFFbw1a, which induces Smad3 ubiquitination." (PMID 25971746, 2015). "Quaking(QKI) is an RNA binding protein and has been shown to serve as a tumor suppressor gene that inhibits the development of several types of tumors, including glioblastoma, astrocytic glioma, oral squamous cell carcinoma, gastric cancer and colon cancer." (PMID 29861871, 2018). "QKI is located on chromosome 6q26-27, which is frequently deleted in astrocytoma and glioblastoma." (PMID 25971746, 2015). "QKI behaves as a tumor suppressor gene (TSG) in glioblastoma multiforme (GBM)." (PMID 26337206, 2015). "QKI suppression induced an aggressive phenotype of glioblastoma cells both in vitro and in vivo." (PMID 25971746, 2015). "To examine whether the QKI isoforms associate with Ago2, a member of the RISC complex, we performed co-immunoprecipitations in the U343, a human glioblastoma cell line known to express the three major QKI isoforms (QKI-5, -6, and -7)." (PMID 20862255, 2010). "Here, we found that several of the most frequently mutated genes in glioblastoma including: EGFR, PTEN, NF1, PIK3R1, RB1, PDGFRA and QKI possessed high 5 hmC levels across intronic regions and further loss of 5 hmC in tumours may reflect a loss of genome integrity." (PMID 27886174, 2016). "Thus, the present study uncovers a novel mechanism that regulates QKI expression in glioblastoma." (PMID 25971746, 2015). "Especially in Glioblastoma Multiforme (GBM), although QKI is not the primary mutation, it still plays a vital role in maintaining the stemness of GBM." (PMID 39479357, 2024).
glioblastoma (continued). "However, the present study found no appreciable alteration of QKI mRNA expression in glioblastoma tissues compared with normal brain tissues, which intimates that translational repression might regulate the loss of QKI expression in glioblastoma." (PMID 25971746, 2015). "Analysis using three publicly available algorithms (TargetScan, PicTar, miRanda) revealed that the QKI-3′UTR contains conserved critical nucleotides that may serve as a legitimate target of miR-148a, which is substantially overexpressed in glioblastoma." (PMID 25971746, 2015). "Immunoblotting analysis showed that QKI expression was reduced in all seven glioblastoma cell lines and in glioblastoma tissues (n = 12) compared with that in primary NHAs and normal brain tissues (n = 3)." (PMID 25971746, 2015). "QKI and PARK2 are located within the same minimal common region on chromosome 6q26-27; PARK2 is a tumor suppressor gene in GBM (glioblastoma), and has an additive effect with QKI in tumor suppression." (PMID 39479357, 2024). "However, combining QKI-3′UTR or SKP1-3′UTR with miR-148a in the glioblastoma cells had no obvious effect compared with transfecting glioblastoma cells with only miR-148a." (PMID 25971746, 2015). "Moreover, real-time PCR analysis revealed no appreciable alteration of QKI mRNA expression in glioblastoma tissue compared with normal brain tissue, which suggests that the reduction of QKI protein in glioblastoma is not due to transcriptional inhibition." (PMID 25971746, 2015). "In the present study, we show that the cytoplasmic QKI isoforms, QKI-6 and QKI-7, but not nuclear isoform (QKI-5), localize with Ago2, PABP1, and TIA1 within stress granules in the U343 glioblastoma cell line and in primary rat oligodendrocytes." (PMID 20862255, 2010).
colon cancer (9 papers, 2013 to 2024). "QKI has been shown to be an RBP with tumour‐suppressant effects in multiple cancers, including colon cancer, whereas little literature linked KCNAB1 or HIST1H1B with cancer." (PMID 38041531, 2024). "miR-155 and miR-221 can regulate the cell cycle and invasive capacity of colon cancer by reducing the production of QKI, while miR-574-5p inhibits the expression of QKI, particularly QKI-6/7, increasing proliferation, migration, and invasion, and decreasing differentiation and cell cycle arrest." (PMID 39479357, 2024). "QKI, as a representative marker of the tumor’s mesenchymal characters, may serve as a biomarker of statin sensitivity in colon cancer where the type II PAK inhibitors have shown their selectivity against mesenchymal-like subgroup." (PMID 36672609, 2022). "Accordingly, in patient-derived colon cancers stratified according to their consensus molecular signature, the same QKI, RBM24, and MBNL2 genes were found to have increased expression in CMS4 tumors, known for their pronounced mesenchymal composition and poor prognosis." (PMID 36346211, 2022).
gastric cancer (8 papers, 2015 to 2025). A primary or metastatic malignant neoplasm involving the stomach. "In addition, we found QKI, which is a tumor suppressor that is associated with cancer prognosis in gastric cancer, and TGFBR2, which is also associated with driver and susceptibility in gastric cancer." (PMID 32127608, 2020). "Notably, CELF2, RBFOX2, PTBP2 and QKI were also involved in the misregulation of AS events in Epstein-Barr virus-associated gastric carcinomas." (PMID 33186122, 2020). "More interestingly, QKI has been found to bind to the introns 2 and 4 of PDIA4 mRNA resulting in a novel circRNA generation in gastric cancer." (PMID 40263288, 2025). "Among these RBPs, QKI was identified as the only protein reported to generate another circRNA by binding to PDIA4 introns 2 and 4 in gastric cancer cells." (PMID 40263288, 2025).
brain tumors (6 papers, 2018 to 2024). "In summary, research has revealed that QKI plays a critical role in angiogenesis, apoptosis, cell growth, and immunity, and it may become a novel biomarker for diagnosis, treatment, and evaluation in brain tumors." (PMID 39479357, 2024). "It is not yet known whether QKI is regulated by methylation in brain tumors." (PMID 39479357, 2024).
heart failure (6 papers, 2022 to 2025). Inability of the heart to pump blood at an adequate rate to meet tissue metabolic requirements. "Recent observations that QKI expression is down-regulated in hearts of heart failure patients indicate that loss of QKI-mediated processes contributes to decreased sarcomere organization in these patients." (PMID 36627242, 2023). "Adult mice with tamoxifen-inducible QKI deletion rapidly developed heart failure associated with severe disruption of sarcomeres, already 7 days after knocking out QKI." (PMID 36627242, 2023). "Most strikingly, loss of QKI in adult cardiomyocytes rapidly induces heart failure, with LV dilation and severe disruption of sarcomeres, and this occurs already 7 days after deleting QKI from the heart." (PMID 36627242, 2023). "In heart failure and cardiomyopathy, RBPMS cooperates with RBM20 to regulate splicing of sarcomeric genes such as TTN, safeguarding contractile integrity, while DDX5 maintains calcium homeostasis through CAMK2D splicing, and loss of QKI results in profound sarcomere disarray and heart failure." (PMID 41399527, 2025). "Indeed, it is suggested that, similar to the loss of Rbm24, aberrant splicing due to the dysregulated expression of MBNL and QKI could contribute to the disease mechanism underlying the pathogenesis of heart failure." (PMID 38535111, 2024). "This is also interesting in light of the recent observation that cardiac QKI expression is downregulated in patients with heart failure." (PMID 37272356, 2023). "In conclusion, we show that QKI depletion in the adult myocardium leads to a DCM that rapidly progresses into heart failure and provide evidence that disrupted sarcomeric organization underlies this contractile defect." (PMID 36627242, 2023). "While deletion of QKI in adult myocardium induced a rapid heart failure phenotype, we also show that forced overexpression of QKI in neonatal cardiomyocytes is able to enhance sarcomere contractility." (PMID 36627242, 2023). "Modulation of QKI activity may serve as a future therapeutic strategy to adapt cardiac isoform expression and improve cardiac function in heart failure patients." (PMID 36627242, 2023). "However, the expression of QKI in cardiac hypertrophy or heart failure was not shown to be significantly changed according to published omics analysis." (PMID 38172650, 2024).
cervical cancer (5 papers, 2017 to 2023). A primary or metastatic malignant neoplasm involving the cervix. "QKI may affect the occurrence and development of cervical cancer by selectively splicing and regulating gene expression." (PMID 37428781, 2023). "In addition, the tumor-promotive role of miR-574-5p has been revealed in other types of cancer, such as cervical cancer and nasopharyngeal carcinoma, respectively targeting QKI and FOXN3, with which interactions were previously discussed in gastric cancer, CRC, and thyroid cancer." (PMID 36671425, 2022).
coronary heart disease (5 papers, 2016 to 2021). "These functional pieces of evidence of the involvement of QKI into the development of cardiovascular conditions are also supported by the GWAS, which pointed at QKI as a contributor to coronary heart disease." (PMID 32194626, 2020). "Findings of GWAS link a number of the identified genes to age-related disorders, such as GAB2 and late onset Alzheimer’s disease, and QKI and coronary heart disease/myocardial infarction." (PMID 31706268, 2019). "Our study suggested that miR-155 inhibition-mediated upregulation of QKI may provide novel idea for the treatment of ischemic heart diseases." (PMID 31191799, 2019).
depression (5 papers, 2012 to 2024). "Currently, comprehensive research regarding the regulatory function of QKI in the onset and development of depression within the central nervous system, as well as its underlying mechanisms, has not been conducted." (PMID 39479357, 2024). "There’s a pronounced decrease in the expression, at both the protein and mRNA levels, of multiple QKI protein subtypes in the cortical, hippocampal, and amygdala regions of individuals with severe depression who died by suicide." (PMID 39479357, 2024). "Pathological changes in neural myelin are widely observed in patients with depression, indicating that the QKI protein may play a vital role in the onset and progression of depression." (PMID 39479357, 2024). "Klempan and colleagues assessed differences in methylation and expression of the oligodendrocyte-specific RNA binding protein (QKI) in suicide completers with a history of major depression relative to age-matched non-suicide controls." (PMID 22738307, 2012). "In addition, the transcription of an oligodendrocyte-specific RNA-binding protein, KH domain-containing RNA binding (QKI), which is important for cell development and myelination, was reduced in the OFC of suicide patients with depression compared to psychiatrically normal controls." (PMID 38891940, 2024).